INS (insulin)
Diseases named in the same sentence as INS in open-access papers (continued):
Sharing a sentence is not in itself a finding about the gene and the disease.
Obesity (continued). "Increased insulin signaling and glucose uptake in adipose tissue in the fed state in sucrose fed mice may thus override the protective effect of fish oil when it comes to protection against obesity-development." (PMID 21738749, 2011). "Thus, this underlying insulin resistant phenotype might add to explain the associations found between the LYPLAL1 variant and obesity." (PMID 21674055, 2011). "In addition, human insulin pharmacokinetics has been shown to be different in patients with type 2 compared with type 1 diabetes and may also be altered by the presence of obesity." (PMID 21410860, 2011). "Going back to obesity research for exemplification of this point, it is scientifically desirable that a laboratory-based biochemical intervention in, for example, leptin and insulin interactions in mice, is potentially transferrable to other experimental systems and other disciplinary approaches." (PMID 21276254, 2011). "Therefore, we wanted to investigate whether the increased insulin sensitivity of TG mice could be able to counteract deleterious effects of high-fat diets even in the presence of obesity." (PMID 21070590, 2011). "However, barley grains may prevent the development of diet-induced obesity by improving insulin sensitivity through altering glucose and lipid metabolism." (PMID 21535898, 2011). "Given the global rise of obesity and related metabolic complications among children, our study thus suggests that improving insulin sensitivity while avoiding harmful immune responses in genetically susceptible individuals may be an important new strategy for early T1D prevention." (PMID 22046124, 2011). "Therefore, the association of rs2877716 with insulin secretion does not appear to be secondary to an underlying association of rs2877716 with birth weight or with obesity." (PMID 21789219, 2011). "With remarkable heterogeneity of obesity in mind, measuring an index of abdominal adiposity such as the waist circumference (WC) is clinically relevant, since among obese individuals, there is a subgroup of abdominally obese patients who are more likely to be insulin resistant." (PMID 20846382, 2010). "Thus, insulin-downregulated omentin-1 production could be behind the inverse relationship between circulating omentin-1 and obesity." (PMID 20380714, 2010). "Treatment of obese rhesus monkeys, which are a model for human obesity and its associated metabolic disorders, with the PPARβ/δ agonist GW501516 increased HDL-cholesterol (79%), and decreased triglycerides (56%), LDL-cholesterol (29%), and fasting insulin levels (48%)." (PMID 20706688, 2010). "The aim of this work was to elucidate the action of the insulin sensitizing PPARgamma on T-lymphocyte infiltration during development of IR, and comparison of the PPARgamma-mediated anti-inflammatory effects of rosiglitazone and telmisartan in diet-induced obesity model (DIO-model) in mice." (PMID 20955583, 2010). "On the other hand, phosphatases that impair the insulin pathway may be elevated in obesity." (PMID 20307313, 2010). "Taken together, our experiments reveal that insulin action in macrophages promotes tissue invasion capacity of these cells in vitro and in vivo, thereby critically controlling high fat diet-associated macrophage invasion and activation in WAT upon induction of obesity." (PMID 20463885, 2010). "However, obesity-related traits and total cholesterol levels exhibited significant association with the E2 DNA copy numbers only in male non-T2DM subjects whereas postprandial 2hr insulin level was significantly higher only in female non-T2DM subjects." (PMID 20624279, 2010). "The lack of consistency between AMH levels and qualitative IVF outcomes in PCOS patients may be influenced by the presence of differing PCOS phenotypes, with either primary ovarian dysfunction or insulin and obesity being the major contributor to reproductive dysfunction." (PMID 20940513, 2010).
Obesity (continued). "Our finding of significantly positive relationships between IFG and BMI and WC are consistent with reports from other studies in different populations and indicate that overweight and obesity could result in higher insulin concentration, secretion and resistance." (PMID 20233452, 2010). "The failure of fructose to effectively suppress ghrelin (impaired satiety), along with the reduced insulin and leptin concentrations, could lead to an increased caloric intake and ultimately contribute to obesity, during chronic consumption of diets high in fructose." (PMID 20798765, 2010). "Skeletal muscle is a primary tissue responsible for insulin-mediated glucose disposal; thus in sarcopenia, the lower total mass of muscle should cause diminished insulin-mediated glucose disposal, independent of obesity." (PMID 22421977, 2010). "Additionally, previous studies have demonstrated that SRT501 and SRT1720, like calorie restriction, enhance oxidative metabolism, protect against diet induced obesity, increase exercise endurance, and improve glucose and insulin homeostasis in rodent models of metabolic disease." (PMID 19284563, 2009). "An understanding of the role of TLR2 and its interactions with other receptors in the adipocyte may yield significant insights into the regulation of inflammation in obesity and may help in the search for new therapeutic targets against obesity-induced impairment of insulin signaling." (PMID 19348674, 2009). "Obesity was clearly detrimental to metabolic health in many respects (lipoprotein and cholesterol profile, insulin sensitivity) but, contrary to our hypothesis, we found little evidence of greater deterioration of health in those offspring prenatally undernourished by global energy deficit." (PMID 19826474, 2009). "Whilst limited data have been presented on the increase of endotoxin in pathological conditions such as obesity and diabetes, no data, as yet, have evaluated the influence of insulin sensitizers, in combination, on inflammatory risk posed by circulating endotoxin." (PMID 19368716, 2009). "A recent report also indicated that high numbers of bifidobacteria may correlate positively with the normalization of inflammatory status and improved glucose tolerance and glucose-induced insulin secretion in an obesity animal model induced by a high-fat containing diet." (PMID 19102766, 2008). "However, a decreased insulin response of the brain beta activity may contribute to the obesity effect of variation in this gene locus." (PMID 18030331, 2007). "Additionally, IL-6 depletion selectively improves hepatic insulin action in obesity." (PMID 16787541, 2006). "Insulin may play a connecting role between obesity and lipid domains." (PMID 15656912, 2005). "In individuals with obesity, there is evidence that the SCT increase in response to prolonged fasting, as well as insulin secretion following an OGTT in response to exogenous SCT administration, is lower compared to normal weight individuals." (PMID 41575482, 2026). "This study aims to analyze the association between the dinner GI and the C385A variant in the FAAH gene with respect to fasting glucose, insulin levels, and HOMA-IR in adults with obesity." (PMID 41750344, 2026). "Principal component analysis (PCA) revealed two dominant components separating metabolic (irisin, HOMA-IR, insulin, BMI) and inflammatory (IL-1β, CCL2) profiles, supporting the distinction between metabolic and inflammatory pathways in obesity." (PMID 42196825, 2026). "Multiple studies have shown that in obesity research model groups, PKA participates in insulin resistance, lipolysis, and BAT thermogenesis by regulating metabolic enzymes and downstream molecules." (PMID 41503874, 2026). "Accumulating evidence demonstrates that obesity leads to suppression of Fasn gene expression in WAT, linking adipose tissue lipogenesis to systemic insulin sensitivity." (PMID 41346765, 2026).
Obesity (continued). "Additionally, similar to the concept of insulin or leptin resistance, obesity and metabolic disturbances may lead to a state of irisin resistance, wherein elevated circulating levels reflect a compensatory response to maintain glucose and metabolic homeostasis." (PMID 41457869, 2026). "While low SPX levels are observed in metabolic disorders such as obesity and type 2 diabetes (T2DM), exercise can raise SPX levels, improving insulin sensitivity and glucose tolerance." (PMID 41597393, 2026). "Numerous clinical studies report that obesity triggers chronic, low-grade inflammation in the liver and pancreas, activating pathways such as NF-κB and SOCS proteins, thereby disrupting insulin signalling." (PMID 41636917, 2026). "Obesity, a central driver of MAFLD, promotes hepatic lipid accumulation and fibrosis through lipotoxicity, insulin resistance, and chronic inflammation." (PMID 40526729, 2025). "We also found that incubating primary adipocytes with insulin robustly increased TPH2 expression, demonstrating that the dramatic upregulation of adipocyte TPH2 in obese mice is driven by obesity-induced hyperinsulinemia." (PMID 40455408, 2025). "The oxidative capacity of mitochondria varies considerably across the spectrum of obesity and MASLD, influenced primarily by body mass but also by age, insulin sensitivity, coexisting T2DM, chronic alcohol consumption, and potentially genetic variants." (PMID 41462693, 2025). "In examining the influence of overweight and obesity, we found significantly elevated levels of GIP and GLP-1 in women with PCOS and elevated weight, along with higher insulin and IR indices." (PMID 40806228, 2025). "The relationship between obesity and MASLD is largely mediated by excess adiposity, which promotes hepatic fat accumulation and insulin resistance." (PMID 40305160, 2025). "The baseline characteristics of patients, categorized by obesity status, revealed significant differences in BMI, ALT, HDL, and Insulin among obese subgroups (P < 0.05)." (PMID 41415809, 2025). "An increase in leptin, insulin, and IGF-1 and a reduction in ghrelin were established in previous studies of patients affected by OW and I–II stages of obesity." (PMID 39970875, 2025). "In BMI-stratified analyses, reductions in insulin and HOMA-IR were observed only among patients with obesity in the high MD adherence group." (PMID 41228493, 2025). "FMTs demonstrates transient metabolic benefits in obesity management, with lean donor FMT inducing short-term (6-week) improvements in microbial butyrogenesis and insulin sensitivity." (PMID 40278960, 2025). "Obesity prevalence was higher in TGD individuals compared to cisgender controls, but lipid profiles and insulin sensitivity remained comparable to the general population." (PMID 40438403, 2025). "Elevated levels of insulin and IGF-1 in obesity create an environment that promotes cell growth and inhibits cell death, accelerating the accumulation of mutations and favoring carcinogenesis." (PMID 41463284, 2025). "When evaluating children with obesity for MASLD, clinicians should consider not only universal markers, such as insulin, but also potentially sex-specific markers such as SUA, ALT, and AST." (PMID 40941570, 2025). "Previous human studies using the FDG‐PET method have shown increased insulin‐stimulated BGU globally across the brain, which suggests that increased insulin‐stimulated BGU in people with obesity and IR is not limited to region‐specific cell types." (PMID 40926735, 2025). "In individuals with obesity, increased FFA release from larger fat tissues disrupts insulin’s ability to suppress lipolysis, leading to even higher blood FFA levels." (PMID 40585342, 2025). "In agreement with previous reports on diet-induced obesity models, feeding male C57BL/6 mice a HFD for 8 weeks led to elevated blood glucose levels and impaired insulin sensitivity, as demonstrated by significantly higher ITT AUC values." (PMID 41471090, 2025).
Obesity (continued). "Increasing evidence suggests that obesity contributes to CKD through multiple mechanisms, including chronic inflammation, hemodynamic alterations, insulin resistance, and lipid accumulation." (PMID 39857056, 2025). "Recognizing this dichotomy has direct clinical implications, suggesting that anti-inflammatory and insulin-sensitizing therapies may be prioritized for the adipose-dysfunction phenotype, whereas antifibrotic and weight-reduction approaches may be more effective in obesity-driven disease." (PMID 41470883, 2025). "Compared with patients who were initiated on insulin, patients who were initiated on GLP1RA were younger, had a lower comorbidity score, frailty score, and diabetic complications, higher prevalence of obesity, and history of genital mycotic infection." (PMID 39860655, 2025). "The researchers have recently found that Curcumin alleviated obesity, reduced inflammation in white adipose tissue (WAT), and improved insulin sensitivity in mice feeding high fat diet." (PMID 40092644, 2025). "We included studies involving adults with T2D or obesity, comparing tirzepatide to placebo, GLP-1 RAs, or insulin." (PMID 40430487, 2025). "A 26-year-old female with T1D for 23 years, managed with a t:slim insulin pump and Dexcom CGM, also with obesity (BMI: 33.6 kg/m2; weight: 80.4 kg; 177 lbs)." (PMID 39707844, 2025). "Conversely, adiponectin expression, which is typically reduced in obesity, was partially restored in ASC complex groups, indicating potential benefits in improving insulin sensitivity and anti-inflammatory responses." (PMID 40508039, 2025). "Addressing obesity through lifestyle changes is a crucial strategy for treating PCOS, as it enhances insulin sensitivity and improves both reproductive and metabolic features." (PMID 40283538, 2025). "While AA blood levels in obesity are linked to decreased insulin sensitivity and β-glucans may affect protein digestion and AA metabolism, data derived from food interventions aimed at controlling AA levels in people with obesity are absent." (PMID 40807584, 2025). "In contrast, fasting serum insulin levels in the newly diagnosed T2DM+obesity group were markedly lower than those in the healthy control and obesity groups (P<0.05)." (PMID 40487757, 2025). "Obesity‐related type I inflammatory cytokines (e.g., IFN‐γ, TNF, leptin, insulin, and palmitic acid) promote TAM PD‐1 expression through mechanistic target of rapamycin complex 1 (mTORC1) and glycolysis‐dependent mechanisms." (PMID 41267926, 2025). "A 14-year-old female with a 3-year history of T1D, managed with an Omnipod insulin pump and Dexcom CGM, presented with a history of polycystic ovary syndrome and obesity (BMI 32.2 kg/m2, weight 83.6 kg)." (PMID 39707844, 2025). "Outside a steroid context, metabolic derangements (fasting glucose/insulin, HOMA-IR) correlate with podocyte injury in obesity-related glomerulopathy." (PMID 41009556, 2025). "A study assessed the impact of RYGB on the metabolic response to orally administered glucose, specifically examining levels of glucose, insulin, VIP, neurotensin, and motilin in eight morbidly individuals with obesity, both pre- and postoperatively." (PMID 41155711, 2025). "In obesity and diabetes, skeletal muscle PI3K/Akt signaling is impaired, while PTP1B expression is elevated, contributing to insulin resistance and muscle atrophy." (PMID 41011082, 2025). "While we did not observe a significant correlation between SESN2 and HbA1c, SESN2 levels had a positive correlation with insulin, HOMA-IR, and the majority of the obesity and adipogenicity indices." (PMID 40433409, 2025). "Obesity induces hypothalamic iNOS and S-nitrosylation of IRβ and AKT, which impairs central insulin signaling and disrupts energy balance." (PMID 41373704, 2025).
Obesity (continued). "In addition, there is evidence suggesting that obesity is associated with lymph node metastases after RP, owing to the deranged prostatic microenvironment and cellular DNA caused by inflammatory factors (IL-6, IL-8, VEGF, leptin) and altered insulin-IGF-1 axis." (PMID 40364176, 2025). "Clinically, pre-pregnancy obesity is a significant predictor of GDM, as body fat percentage is proportional to insulin resistance." (PMID 40731821, 2025). "A dual GLP-1/GDF15 agonist led to greater reductions in body weight, food intake, insulin, fasting glucose, and triglycerides compared to individual treatments, highlighting GDF15’s potential in obesity management." (PMID 40530451, 2025). "Those with obesity in SCI (defined as BMI ≥ 22) had increased total and trunk mass and fat percentage, unfavorable lipid profiles and evidence of insulin insensitivity." (PMID 40781458, 2025). "Complementary meta-analytic evidence shows that exercise training (aerobic and combined modalities) lowers fasting glucose, insulin, and HOMA-IR, with additional support for resistance-training–specific benefits in adults with overweight/obesity." (PMID 40981168, 2025). "Twenty-four patients with obesity and T2DM undergoing insulin therapy were randomly assigned to receive either exenatide (a glucagon-like peptide-1 receptor agonist) or a placebo twice daily for 12 weeks." (PMID 41109135, 2025). "Herein, elevated insulin was a common and key factor in the development of MASLD in children with obesity, aligning closely with conclusions from previous research." (PMID 40941570, 2025). "In women with obesity: higher nighttime carbohydrate intake → higher 2 h OGTT glucose and lower insulin secretion." (PMID 41295235, 2025). "Adiponectin is negatively correlated with the degree of obesity, maintaining anti-inflammatory effects, FAO, and insulin sensitivity." (PMID 40725208, 2025). "Finally, translating preclinical findings into well-controlled human studies is essential to determine whether AX can effectively improve muscle metabolism, insulin sensitivity, and lipid handling in individuals with obesity, metabolic syndrome, or type 2 diabetes." (PMID 41515196, 2025). "Several studies have explored the addition of metformin to progestin therapy, motivated by its anti-proliferative and insulin-sensitizing effects, particularly in patients with metabolic comorbidities such as PCOS or obesity." (PMID 41463224, 2025). "Among male children with obesity, those in the MASLD+ group had significantly higher levels of insulin, ALT, AST, SUA, and high-density lipoprotein (HDL) than those in the MASLD− group." (PMID 40941570, 2025). "In this study, we show that children and adolescents with obesity and moderate–severe OSA have lower insulin clearance and higher hepatic insulin resistance, but similar insulin secretion, compared to children with mild OSA." (PMID 40365648, 2025). "Systemic low-grade inflammation accompanying obesity and T2D—marked by cytokines such as TNF-α and IL-6—impairs insulin signaling and recruits immune cells into insulin-sensitive tissues." (PMID 40871736, 2025). "This suggests that the activation of the AMPK/ACC axis underpins the potent hypoglycemic, hypolipidemic, and anti-obesity effects of Talh honey, consistent with AMPK’s established role in inhibiting lipogenesis and promoting insulin-stimulated glucose uptake." (PMID 40901285, 2025). "Enhancing insulin and leptin signaling through the deletion of specific phosphatases like PTP1B and TCPTP in these neurons prevents diet-induced obesity by increasing energy expenditure and stimulating the browning of WAT." (PMID 40130157, 2025). "Mice with obesity show increased ERK1/2 activity, and its hepatic depletion improves systemic insulin action." (PMID 40004184, 2025).